BRAF (B-Raf proto-oncogene, serine/threonine kinase)
Diseases named in the same sentence as BRAF in open-access papers (continued):
Sharing a sentence is not in itself a finding about the gene and the disease.
tumor (continued). "On the background of this difference, it is possible that those patients who had BRAF-positive AM and were previously given BRAF and MEK inhibitors in combination achieved a fast regression of the tumor burden." (PMID 35885042, 2022). "Consequently, inhibition of FAK may provide a reasonable and tumor selective strategy to sensitize MM to cell death, irrespective of their BRAF/NRAS mutation status." (PMID 35022419, 2022). "Two additional tumours obtained a calibrated score of 0.7 for this methylation class, including one harbouring a RNF130:BRAF fusion." (PMID 35836307, 2022). "Regorafenib inhibits kinases and cellular pathways involved in angiogenesis and tumor growth, such as the VEGFR1-3, FGFR1-2, c-KIT, PDGFRα/β, RET, and BRAF." (PMID 36612019, 2022). "However, regardless of BRAF mutation, cells clustered together by tumor regions, which may imply that the single BRAFV600E mutation may not cause dramatic changes in global gene expression patterns of cancer cells." (PMID 35974387, 2022). "One such study of patients treated with a BRAF inhibitor showed an early increase in CD8 + T-cell infiltrates after 3–15 days on treatment, which correlated with a decrease in tumour size." (PMID 35366166, 2022). "When targeting anti-angiogenesis, MTDs can simultaneously target multiple proteins that promote tumor growth such as RET, FLT3, and BRAF, which contribute to the overall anti-tumor effect." (PMID 35463356, 2022). "This study retrospectively analyzes tumor growth velocity (TGV) of pLGG before surgery and after IR to investigate the impact of surgical extent, tumor location and molecular BRAF status on postoperative residual tumor growth behavior." (PMID 36319795, 2022). "Therefore, our findings confirm that a fraction of mCRC patients carries sub-clonal RAS/BRAF variants that might not be identified by testing a biopsy of a single tumor site and that can be identified by cfDNA testing." (PMID 35205799, 2022). "This notion is supported by the combination of BRAF and MEK inhibition, which boosts the expansion of tumor-specific T cells and the abundance of TCR repertoire, which is due to the induction of TCF7 and T-bet." (PMID 36145516, 2022). "We previously identified 11 patients treated with BRAF and/or MEK inhibitors at the Vanderbilt-Ingram Cancer Center with matched tumor sections obtained pre-treatment and at disease progression." (PMID 35058553, 2022). "BRAF mutants generally activate MEK/MAPK and regulate the downstream factor ETV1, thereby promoting ICC proliferation and transformation into a tumor." (PMID 36497489, 2022). "We evaluate the health economic impact of employing tumor molecular testing to guide treatment for patients diagnosed with PLGG, particularly the avoidance of radiation therapy (RT) for patients with BRAF-fusion." (PMID 34980048, 2022). "While BRAF/MEK inhibitors allow for rapid disease control, and CPI can evoke durable tumor responses, primary and secondary resistance frequently limit treatment efficacy." (PMID 35565212, 2022). "For PTMC with a tumor size > 5 mm, LN metastasis was found in eight (80.0%) CNV+ patients and in seven (63.6%) CNV– and BRAF+ patients (OR 2.283, p = 0.635)." (PMID 36313748, 2022). "In a mouse model of BRAF V600E mutant melanoma, Pexidartinib combined with adoptive cell transplantation decreased TAM and increased tumor-infiltrating lymphocyte levels." (PMID 35874717, 2022). "In line with these, combinatorial treatment with a BRAF and a YAP1 inhibitor has been shown to decrease tumor growth." (PMID 35558554, 2022). "However, we also observed that the highly scoring patches identified by the TCGA model failed to represent classical histopathological features of BRAF mutation; indeed, seven out of nine highly scoring tiles in this group showed abundant artifacts or no tumor tissue." (PMID 35469069, 2022).
tumor (continued). "Recent reports showed that the combination of anti-PD-1/PD-L1 therapy with BRAF and MEK inhibitors, VEGF inhibitors, chemotherapy, radiation, and photodynamic therapy would promote tumor-infiltrating T cells and the anti-tumor activity of ICIs." (PMID 36139451, 2022). "In the TIME of tumors treated with the BRAF inhibitor, anti-tumor-specific CD8+ T cells were enriched due to increased tumor antigen expression." (PMID 36145516, 2022). "For example, CDK4/6 inhibition restricts optimal T cells expansion, and when used in combination with BRAF/MEK-targeted therapies, depletes immune-potentiating myeloid subsets from the tumor microenvironment." (PMID 35444175, 2022). "Tumour growth was measured on alternate days, showing that knockdown of EEF2K reduced the tumour growth by up to 65%, in a manner similar to cells in which BRAF had been targeted and compared to the siScramble control (p < 0.0001)." (PMID 35408842, 2022). "This study aimed at identifying a BRAF and MEK inhibitor combination with superior anti-tumor activity to the three currently approved combinations." (PMID 36230853, 2022). "Combination of PD-L1/PD-1 and BRAF/MEK inhibitors improves T-cell toxicity towards cancer cells, and delays tumor resistance." (PMID 35847840, 2022). "We re-analysed this tumor by using an ARCHER® FusionPlex NGS panel and were able to validate a fusion of KIAA1549 exon 14 to BRAF exon 8 in this case." (PMID 35361262, 2022). "In 41 MSI-H tumors, 9 BRAF MT were found (21.9%) and 18 K- and N-RAS MT (43.9%), 14/41 MSI-H tumor were all wild type." (PMID 33675399, 2021). "BRAF(PLX4720) or MEK kinase inhibitors(PD0325901) exhibit a certain inhibitory effect on the survival, proliferation, and migration of tumour cells." (PMID 34923978, 2021). "As AIM2 is reported as a tumor suppressor in CRC, we want to investigate its functional role in BRAF-mutant CRC and try to pave the way for CRC treatment." (PMID 33842454, 2021). "In preclinical models, CDK4/6 inhibitors overcome BRAF/MEK inhibitor resistance, leading to sustained tumour regression; however, the metabolic response to this combination has not been explored." (PMID 33572972, 2021). "These patients are treated with antiangiogenic multitarget tyrosine kinase inhibitors including lenvatinib and sorafenib, and specific inhibitors for BRAF-, MEK- or ALK-mutant tumours." (PMID 34062862, 2021). "The ITM deposits of 40 patients treated with DPCP were subjected to biomarker analysis for BRAF status, CD8 and PD-1 expression on tumor-infiltrating lymphocytes (TILs), and tumor PD-L1 expression." (PMID 32542563, 2021). "As part of the Reproducibility Project: Cancer Biology, we published a Registered Report that described how we intended to replicate selected experiments from the paper ‘Kinase-dead BRAF and oncogenic RAS cooperate to drive tumor progression through CRAF’." (PMID 34874009, 2021). "Common mutations in this context involve, for example, the activation of oncogenes, such as BRAF and RAS and the inactivation of key tumor suppressors, such as PTEN and CDKN2A." (PMID 34831311, 2021). "Small molecule inhibitors of mutant BRAF were developed to block protein kinase activity and prevent activation of MAPK/ERK signaling in tumor cells." (PMID 34025662, 2021). "Although a relatively small group of patients was taken into consideration, the BRAF V600E positivity clearly increased with a higher EU-TIRADS score, with the strongest correlation found between hypoechogenicity and taller-than-wide tumor shape." (PMID 34070605, 2021). "The highest benefit was observed in patients with RAS, BRAF, and EGFR wild-type tumor assessed by basal plasma circulating tumor DNA (ctDNA) analysis." (PMID 34830870, 2021). "We were intrigued to see that compared to subtyping efforts based on gene expression, also microbial profiling identified one subtype (TMS1) enriched in BRAF mutant, MSI-H, right-sided tumours." (PMID 34638284, 2021).
tumor (continued). "Of 1630 COIN trial patients enrolled in the treatment arms of interest, tumour tissue for CMS classification was available for 323 patients (19.8%), of which 140 (43.3%) were RAS and BRAF wildtype." (PMID 34253874, 2021). "In order to check for this possibility, we calculated the ratio between the measured WT DNA in BRAF assay and the mean value of all measured WT amounts of DNA in KRAS assays in tumor samples." (PMID 33669856, 2021). "The tumor progression seen in the patient treated with single-agent vemurafenib suggested that combining BRAF and MEK inhibition would be preferable for prolonged and durable control of tumor growth." (PMID 35155453, 2021). "All MM patients harbored a BRAF and NRAS wild-type tumor and received a median of 3 lines of prior therapies including ICIs, whereas the majority of patients with RCC received at least 3 lines of tyrosine kinase inhibitors (TKIs)." (PMID 34777395, 2021). "Firstly, several vital prognostic factors, such as KRAS, BRAF, microsatellite instability (MSI), tumor regression grade, circumferential resection margin (CRM), were inaccessible in the SEER database, thus did not incorporate in the proposed nomogram." (PMID 34322745, 2021). "Tumor cells were isolated from mice of both genotypes (BP and BPN) that had been placed on BRAF/MEK inhibitor-diet or control chow for one week." (PMID 33821796, 2021). "In particular, Sorafenib interacts with BRAF, BRAFV600E, cKIT, and FLT3 on tumor cells and VEGFR2–3 and PDGFRβ on tumor endothelial cells." (PMID 34205656, 2021). "This study provides an integrated study including a cellular model, animal model, and tumor PDO, which provides evidence to understand the pathogenesis of CRC with BRAF-mutant, as well as new strategies for manipulation of CRC." (PMID 33842454, 2021). "BRAF is one of the key genes of the MAPK/ERK signaling pathway, which is an important pathway for regulating tumor proliferation and apoptosis." (PMID 33777735, 2021). "Recently, dual BRAF and MEK inhibition was also shown to induce anti-tumor immunity via the induction of pyroptosis; a type of inflammatory cell death that promotes DC activation and subsequent T cell immunity." (PMID 34025662, 2021). "Furthermore, our comprehensive analysis on CRC tumor samples gives preliminary hints that the switch from CMS1 to CMS4 might be independent of the microsatellite instability, hypermethylation, or mutation status of the cancer driver BRAF." (PMID 35008299, 2021). "For these reasons, the KRAS status of liquid biopsy tends to be less reflective in NRAS, BRAF, EGFR, and MSI of the origin tumor." (PMID 34442609, 2021). "The comparative analyses include ddPCR BRAF V600 screening kit from BioRad, anti-BRAF V600E IHC staining and NGS on matched tumor samples from the same individuals." (PMID 33907234, 2021). "Dual inhibition strategies, such as MEK inhibition in combination with BRAF, BET, and CDK4/6 inhibitors have been employed in neuroblastoma, but studies have reported limited anti-tumor activity or concerns of eventual escape and resistance." (PMID 34572875, 2021). "A biopsy of the original tumor was sent for panel-based genomic testing in 2019 which identified the tumor as KRAS WT, NRAS WT, BRAF WT (Caris, Irving, TX, USA)." (PMID 34504655, 2021). "This includes tumor gene sequencing as well as the use of specific targeted drugs for tumors with targetable alterations (e.g., EGFR, ALK, ROS1, NTRK, BRAF, or HER inhibitors)." (PMID 34070597, 2021). "The microenvironment in which the tumour resides, the tumour microenvironment (TME), can influence the efficacy of the immunotherapies and the intracellular targeted therapies such as BRAF inhibitors." (PMID 34439879, 2021). "BRAF-mutant GBM are very rare, especially in adult populations; however, differences in tumor location, survival rates, and global gene expression profiles set this set of tumors apart from other GBM." (PMID 34625582, 2021).
tumor (continued). "The combinations of BRAF and MEK inhibitors have demonstrated immediate anti-tumor effects, which culminate in tumor regression and symptomatic improvement." (PMID 34065877, 2021). "BRAF inhibitors were combined with MEK inhibitors in clinical trials due to their synergism, which can delay tumor progression and increase acquired resistance." (PMID 34831002, 2021). "Our study also demonstrates the high concordance of ctDNA and tumour tissues for the molecular characterisation (KRAS and BRAF status), which was shown in many previous studies." (PMID 34294055, 2021). "The objective of the study is to investigate the effect on pathological tumor response in resectable tumors and to observe objective tumor response in KRAS or BRAF mutant metastatic tumors (NCT03146962)." (PMID 34717701, 2021). "On the other hand, the presence of BRAF fusion in the tumor suggests the potential use of target therapy, such as MEK inhibitors, while the use of BRAF inhibitors are indicated and useful when the BRAFV600 mutation is present." (PMID 34574050, 2021). "The nature of imbalance in FRMD5 intracellular yield and expression observed in cells harboring BRAF-wt and BRAF V600E is not clear and might result from overall unequal gene expressional profiles, which determines phenotypic features and unique tumor biology cells harboring these mutations." (PMID 34201607, 2021). "Although these compounds had comparable binding capacity to BRAF-V600E in vitro (Vemurafenib = 27 nM, SJF-0628 = 39 nM, SJF-0661 = 64 nM), SJF-0628 had significantly stronger anti-tumor activity." (PMID 34249939, 2021). "This was expected for tumor P026, which is MSI, but unexpected for P014, which was diagnosed as BRAF‐mutant, however MSS." (PMID 34409732, 2021). "In addition, tumor deposits, serum CEA levels, tumor regression score, circumferential resection margins, lymph vascular invasion, perineural invasion, microsatellite instability and RAS and BRAF mutations should also be considered in the prognostic prediction and treatment decision making." (PMID 33613748, 2021). "The mRNA expression level and prognostic significance of KRAS, BRAF, and KIT were checked using the UALCAN database, in the heatmap representation, normal tissue (n = 1), primary tumor (n = 104), and metastatic cases (n = 368)." (PMID 34769348, 2021). "Negative samples showed distinct expression profiling; however, they resemble those observed in BRAF V600E or RAS positive tumors in many different aspects, with highlights to tumor infiltrating immune cells." (PMID 34680332, 2021). "However, patients terminating BRAF ± MEKi in this retrospective study for other reasons than PD showed a higher rate of tumor progression (69.2%) and a shorter PFS upon termination of TT, which might be explained by the longer overall observation period covered in our study." (PMID 34065877, 2021). "Tumor biopsies were examined as wild-type KRAS (exon 2, 3, 4), NRAS (exon 2, 3, 4) and BRAF V600E for all patients included in this study." (PMID 34335943, 2021). "Among the six patients with high PD-L1 and BRAF V600E mutant NSCLC, two patients had major tumor shrinkage while two other patients had hyperprogression." (PMID 34926258, 2021). "In contrast, mutant BRAF, ATM, LRP1B, FAT4, FMN2, TRRAP, and ROS1 had higher stromal score (except ATM), immune score and ESTIMATE score, and the tumor purity was lower than the wild-type." (PMID 33836681, 2021). "Dual inhibition of both PI3K and BRAF, a combination strategies targeting BRAF and PI3K pathways was found to be effective in suppressing the tumor formation." (PMID 37305163, 2021). "KRAS mainly activates the PI3K/AKT/mTOR and BRAF/MEK/ERK pathways and activates inflammatory pathways such as the NFκB signaling pathway, which is required for tumor maintenance and malignant transformation." (PMID 34336638, 2021).
tumor (continued). "Such investigations are clinically relevant given the possibility of disease progression after cessation of BRAF/MEK-directed TT and the subsequent exigency to efficiently rechallenge tumor treatment." (PMID 34065877, 2021). "Triplet targeted therapy of BRAF-MEK-CDK4/6i with OT-1 ACT led to sustained and robust anti-tumor responses in BRAFi sensitive YOVAL1.1." (PMID 34944961, 2021). "When disease control is the goal, CT doublet plus anti-EGFR is recommended as the 1L treatment for RAS/BRAF WT left-sided tumor, and CT doublet plus anti-VEGF is recommended for RAS/BRAF WT right-sided tumor." (PMID 34868987, 2021). "This study highlights the degree of selectivity achievable with degradation-based approaches by targeting mutant BRAF-driven cancers while sparing BRAFWT, providing an anti-tumor drug modality that expands the therapeutic window." (PMID 33568647, 2021). "Moreover different clinical studies have suggested that the dysbiotic signature of CRC might be different according to the tumor characteristics (KRAS, BRAF mutations, and DNA mismatch repair MMR alterations) and/or tumor sidedness (proximal or distal location)." (PMID 34063108, 2021). "The majority of these alterations were related to defects in DNA repair, making tumours potentially sensitive to PARP inhibition, but frequent targetable alterations were also seen in BRAF, MTOR signalling as well as several other genes." (PMID 34647903, 2021). "Although, at mRNA level, CCND1 expression wassignificantly lower in tumor samples (P<0.001), SOX2, BRAF,TNFA, and VEGF expression was increased in malignant tissuescompared with normal adjacent samples (P<0.05)." (PMID 34308569, 2021). "Conversely, the higher rate of co-occurrent alterations, either “passengers” or even “drivers”, in MET, KRAS, BRAF and EGFR-driven tumors, suggests a branched clonal evolutionary process existing from the early steps of tumor progression." (PMID 33946519, 2021). "Current guidelines for the therapeutic management of patients with mCRC recommend KRAS, NRAS, BRAF and high microsatellite instability (MSI-H) profiling on tumor tissue samples." (PMID 34943612, 2021). "Regorafenib is an oral multikinase inhibitor of several protein kinases, including kinases involved in tumor angiogenesis (VEGFRs 1–3), oncogenesis (KIT, RET, RAF1, BRAF, and BRAFV600E), and development of the tumor microenvironment (PDGFR and FGFR)." (PMID 33337518, 2021). "In addition to a panel of gene analysis of the tumour, mutation analysis of the BRAF, KRAS and NRAS genes and Mismatch Repair (MMR) status (Microsatellite instability, MSI, Immunohistochemistry, IHC, for MMR genes) will be performed on the selected tumour sections." (PMID 34544470, 2021). "Short term treatment enhanced tumour infiltration of CD8+ T-cells, which subsequently decreased, but combining short term BRAF and MEK inhibitor therapy with anti-PD-1 ICB increased their anti-tumour activity." (PMID 34960140, 2021). "We observed a significant correlation between BRAF V600E and a higher EU-TIRADS score (p-value = 0.02) with a correlation between hypoechogenicity and taller-than-wide tumor shape in analysed patients." (PMID 34070605, 2021). "Following early suppression of glucose consumption upon treatment with the BRAF inhibitor vemurafenib, subsequent increases in glucose uptake as assessed using FDG uptake in treated tumours tightly correlated with emergence of resistance." (PMID 34830962, 2021). "The sequencing of protein-coding exons, e.g., KRAS, BRAF and PIK3CA, in circulating tumor DNA (ctDNA) samples from MM patients revealed that it predicted 96% of mutations detected in matched BM-derived tumor DNA samples with >98% specificity." (PMID 34299097, 2021). "The multikinase inhibitor Sorafenib, a first generation BRAF inhibitor, antagonises RAF serine/threonine kinases and receptor tyrosine kinases, reducing tumour proliferation and tumour cell survival." (PMID 33562337, 2021).